VDR (vitamin D receptor)
Diseases named in the same sentence as VDR in open-access papers (continued):
Sharing a sentence is not in itself a finding about the gene and the disease.
prostate carcinoma (continued). "Therefore, we conducted a meta-analysis to establish the association between VDR Cdx2 and ApaI polymorphisms, and prostate cancer risk." (PMID 27553621, 2016). "Furthermore, polymorphisms in the VDR gene are associated with prostate cancers; this finding supports the role of VDR in the risk of some type of cancers." (PMID 26179909, 2015). "A few studies based on Asian cohorts as well as patients in western countries indicated that vitamin D receptor polymorphisms are associated with the incidence of prostate cancer, and vitamin D receptor may be a therapeutic target for BPH." (PMID 25685834, 2015). "VDR Cdx2 AA genotype was associated with prostate cancer in men with low 25(OH)D (≤15 ng/mL) (p interaction = 0.02) and with aggressive and high-grade prostate cancer in men with low 25(OH)D and 1,25(OH)2D (p interaction = 0.04 and 0.01, respectively) compared with men with normal levels." (PMID 25488826, 2015). "Variants in the VDR have been associated with advanced stage or high Gleason grade, with a recent meta-analysis of 13 studies, including data from this study, finding an association between three VDR polymorphisms (ApaI, BsmI and TaqI) and prostate cancer grade." (PMID 25488826, 2015). "Studies have demonstrated that rs10735810 and rs1544410 SNPs in VDR might modulate the risk of breast, skin, and prostate cancers, as well as other forms." (PMID 25266489, 2014). "However, inverse associations were reported in this population when five other VDR SNPs were examined in relation to UV exposure and prostate cancer risk." (PMID 20049159, 2010). "In conclusion, the present study indicated that VDR gene polymorphisms may be associated with prostate cancer risk in the southern Chinese Han population, and these associations may largely depend on population characteristics and geographic location." (PMID 19961572, 2009). "Moreover, vitamin D status, measured by 25(OH)D in plasma, interacts with the VDR FokI polymorphism and modifies prostate cancer risk." (PMID 17388667, 2007). "Consequently, VDR-linked Taq1 polymorphisms might be regarded as a possible diagnostic biomarker for the susceptibility to prostate cancer." (PMID 39335182, 2024). "Therefore, it is not clear how micronutrients that potentially interact with the VDR might impact the association of serum 25(OH)D and prostate cancer in the context of increased serum IGF-axis proteins." (PMID 28417914, 2017). "Future studies with a large population cohort focused on genotyping additional polymorphisms to capture more of the variations in the VDR gene, and haplotype analysis to elucidate the role of the VDR gene as a prostate cancer risk factor may benefit the expansion of significant data." (PMID 27066374, 2016). "Among more than 470 polymorphisms in the VDR gene, there may be six polymorphisms including the Fok1, Cdx2, Bsm1, Apa1, and Taq1 SNPs, and Poly(A) microsatellite to be frequently studied in relation to risk of cancer including prostate cancer." (PMID 21991434, 2011). "Our experiments provide evidences that genetic polymorphisms in the VDR gene may be potential risk factors for prostate cancer in the Han population of southern China and the susceptibility to prostate cancer is associated with ethnicity and geographic location." (PMID 19961572, 2009). "Our large sample size, especially for patients with clinical aggressive prostate cancer, allowed us to assess the associations of 25(OH)D and 1,25(OH)2D, individually and jointly, with total and aggressive disease, as well as their potential interactions with the VDR polymorphisms." (PMID 17388667, 2007). "We studied 210 prostate cancer cases and 155 controls to determine whether vitamin D receptor (VDR, Taql and Fokl variants), tyrosinase (TYR, codon 192 variant) and melanocortin-1 receptor (MC1R, Arg151Cys, Arg160Trp, Val92Met, Asp294His and Asp84Glu variants) genotypes are associated with risk." (PMID 11720436, 2001).
prostate carcinoma (continued). "Validation in three clinical cohorts revealed that the footprint of VDR signaling was most apparent in AA prostate cancer." (PMID 37082578, 2023). "It is reasonable to suggest that the VDR stands at the crossroads of biopsychosocial signaling that impacts prostate cancer by a distinct pattern of VDR genomic binding in a manner that is governed by African genomic ancestry." (PMID 37082578, 2023). "In contrast, expressions of the AR and VDR were unchanged between EA and AA prostate cancer samples." (PMID 37082578, 2023). "These VDR functions were significantly corrupted in the isogenic AA RC43T prostate cancer cells, and significantly distinct from EA cell models." (PMID 37082578, 2023). "The clinical impact of VDR cistrome-transcriptome relationships were tested in three different clinical prostate cancer cohorts." (PMID 37082578, 2023). "Together, these approaches revealed that VDR signaling qualitatively and quantitatively differed between AA and EA cells, and that BAZ1A expression in AA prostate cancer regulated the capacity of the VDR to control immunomodulatory and circadian signaling." (PMID 37082578, 2023). "For example, miRNA that predicted progression from HGPIN to prostate cancer in AA men were highly enriched for VDR cistrome data, as were genes that responded in prostate tumors from men receiving vitamin D3 supplementation prior to radical prostatectomy." (PMID 37082578, 2023). "In prostate cancer, VDR knockdown induces cell apoptosis and inhibits cell proliferation and tumor growth in immune-incompetent nude mice." (PMID 37524814, 2023). "In this manner, we were able to test how components of the VDR complex identified in cell lines were plausibly impacting VDR-target gene relationships in prostate cancer in patients." (PMID 37082578, 2023). "The current study aimed to define VDR genomic signaling in the context of the racial health disparities in prostate cancer, given that the AA patient group appears to be most acutely vulnerable to low serum vitamin D3." (PMID 37082578, 2023). "The epigenetic status of the VDR-targeted gene transcription start sites was regulated by altering the DNA methylation and H3K4me2/H3K9Ac levels within prostatic cancer." (PMID 35765066, 2022). "The VDR protein expression data are consistent with our previously published in vitro work with C4-2 human prostate cancer cells." (PMID 34199743, 2021). "In previous work, we had observed that the selective prolactin receptor modulator, S179D PRL, sensitized prostate cancer cells in vitro to physiological concentrations of calcitriol through an ability to increase expression of the vitamin D receptor." (PMID 33179012, 2020). "The VDR is an important positive regulator of p21 expression and hence an important inhibitor of growth and promoter of apoptosis in prostate cancer cells." (PMID 33179012, 2020). "In regards to the evaluation of VDR, it is important to note that lesions in the G_1 group showed a very low number of nuclear VDR positive prostate cancer cells." (PMID 31614564, 2019). "Variation of SNPs on VDR and CYP27A1 was associated with lethal prostate cancer even after adjustment for 25(OH)D levels." (PMID 30249031, 2018). "We found that 25D3 largely regulated the expression of its target genes in common with 1,25D3 via the VDR when the VDR is expressed in prostate cancer cells, although the anti-proliferative activity of 25D3 was absent." (PMID 29899561, 2018). "This evidence candidates nuclear VDR as a reliable prognostic and/or predictive marker of prostate cancer occurrence." (PMID 30627063, 2018). "Of particular interest, the role of the VDR on the pathogenesis and outcome of prostate cancer has been discussed widely." (PMID 29899561, 2018). "These SNPs of the VDR gene have been related to chronic diseases of inflammatory, infectious and autoimmune etiology such as prostate cancer, Graves disease, Hashimoto’s thyroiditis, Addison’s disease and type 1 and T2D." (PMID 29795525, 2018).
prostate carcinoma (continued). "More recently, the relationship between the VDR and prostate cancer has been investigated rigorously." (PMID 29899561, 2018). "Using a VDR knockdown approach, the current in vitro and in vivo studies aimed to further define the role of the VDR in the regulation of breast and prostate cancer growth." (PMID 28944088, 2017). "Our study is the first to explore VDR action in prostate cancer using next generation RNA sequencing of the TMPRSS2:ERG positive VCaP cell line." (PMID 28591703, 2017). "Despite some promising in vitro and pre-clinical studies, the capacity of activated VDR to inhibit prostate cancer growth in humans is unclear." (PMID 28591703, 2017). "Analysis of the top 5 Hallmark gene set pathways shows a reduction in c-Myc and E2F pathways by both agonists consistent with our understanding of VDR signaling in the LNCaP lineage of prostate cancer cells." (PMID 28591703, 2017). "Clinical research into the role of vitamin D and VDR status in breast and prostate cancer has remained controversial." (PMID 28944088, 2017). "Transcriptome analysis of VDR signaling in prostate cancer cells has been limited to microarray analysis and has not included a TMPRSS2:ERG positive cell line." (PMID 28591703, 2017). "Additional analysis showed that the percentage of vitamin D receptor positive nucleus in the prostate was reduced in patients with prostate cancer." (PMID 28423553, 2017). "Inadequate dietary vitamin D results in elevated proliferation in mouse prostate epithelium and some prostate cancer cell xenograft studies have shown a reduction in tumor growth upon VDR activation." (PMID 28591703, 2017). "Several previous studies have been reported to examine the association between Vitamin D receptor (VDR) gene Fok I polymorphism and susceptibility to prostate cancer (PCa), however the results remain inconclusive." (PMID 27788484, 2016). "Variants in VDR, CYP24A1, and CYP27B1 were associated with progression to prostate cancer-specific mortality in a case-only study (n = 1,294)." (PMID 25488826, 2015). "The current study aimed to examine the gene specific mechanisms by which the actions of the vitamin D receptor (VDR) are distorted in prostate cancer." (PMID 23098689, 2013). "The importance of VDR in negatively regulating prostate cancer progression is further confirmed in the LPB-Tag model of prostate in VDR knockout versus VDR wild-type mice." (PMID 21991434, 2011). "In prostate cancer cells, the growth inhibitory actions of 1,25(OH)2D require the presence of the vitamin D receptor (VDR), a ligand-inducible transcription factor." (PMID 20070897, 2010). "Our previous study suggests that LXR, VDR and androgen receptor (AR) signaling form a complex interaction in the prostate cancer LNCaP cells." (PMID 19787078, 2008). "Recently, it has been shown that elevated SMRT levels result in suppression of target genes for the vitamin D receptor (VDR) in prostate cancer cells and in apparent hormonal insensitivity." (PMID 19455236, 2007). "Despite these several limitations, the study raises insights (genomic analyses) into the impact of vitamin D receptor expression in prostate cancer that may interest readers." (PMID 39963174, 2025). "Gene set enrichment analysis for VDR-high and VDR-low subsets of prostate cancer." (PMID 39963174, 2025). "Prostate cancer cells express the VDR, suggesting that vitamin D may play an important role in the pathogenesis and progression of this cancer." (PMID 40362574, 2025). "Multiple linear regression model of VDR methylation loci in prostate cancer." (PMID 39963174, 2025). "African American (AA) prostate cancer associates with vitamin D3 deficiency, but vitamin D receptor (VDR) genomic actions have not been investigated in this context." (PMID 37082578, 2023).
prostate carcinoma (continued). "Finally, partial correlation analyses established that BAZ1A and components of the VDR complex identified by RIME significantly strengthened the correlation between VDR and target genes in AA prostate cancer only." (PMID 37082578, 2023). "In the current study, we aimed to establish VDR genomic functions in AA and EA prostate cancer with the goal to assess how this may contribute to health disparities." (PMID 37082578, 2023). "Finally, we examined how these VDR cistrome-transcriptome relationships that were identified in cell line models were detected in three clinical prostate cancer cohorts of AA and EA patients." (PMID 37082578, 2023). "Again, supporting a role for the VDR function in prostate cancer health disparities, VDR transcriptional actions are significantly stronger in AA patients with prostate cancer compared with EA patients, with significantly more dynamic regulation of genes implicated in control of inflammation." (PMID 37082578, 2023). "However, prostate cancer bone metastases (n = 8) demonstrated a high nuclear VDR expression compared to the cytoplasm more frequently." (PMID 36362766, 2022). "Notably, all prostate cancer bone metastases (n = 8) demonstrated a high nuclear VDR protein expression in this study cohort." (PMID 36362766, 2022). "Interestingly, prostate cancer bone metastases had a low VDR protein expression in the cytoplasm more often compared to the nucleus." (PMID 36362766, 2022). "Consistently, elevated risk of prostate cancer in certain populations may be associated with the difference in the distribution of prostate cancer risk associated genotypes i.e. AR, SRD5A2 and VDR." (PMID 34535145, 2021). "Interestingly, transcriptional activity of VDR in prostate cancer tissue was strongly regulated by lysine-specific demethylase 1A (LSD1), a key regulator of the androgen and estrogen receptors." (PMID 32560347, 2020). "VDR is widely expressed including in prostate and in prostate cancer." (PMID 28591703, 2017). "In order to investigate whether the effects of VDR ablation on cancer cell behavior are reproducible across different types of cancer, we next studied the human prostate cancer cell line, PC3, in analogous experiments." (PMID 28944088, 2017). "The goal of the study was to investigate possible association of some single nucleotide polymorphisms (SNPs) in the VDR gene (the FokI, BsmI, ApaI and TaqαI loci), and the CYP17 gene (the MspA1I locus), and 0 or 9 TA repeats in the SRD5A2 gene, and prostate cancer (PCa) among Lebanese men." (PMID 28240015, 2017). "The present study measured prostatic VDR and NF-κB p65 subunit in patients with prostate cancer." (PMID 28423553, 2017). "Our results indicate that the unliganded VDR possesses hitherto unknown functions to promote breast and prostate cancer growth, which appear to be operational not only within but also outside the bone environment." (PMID 28944088, 2017). "However, contrary to this assumption and our expectations, we found that silencing of the VDR in breast and prostate cancer cell lines consistently resulted in reduced cell growth and increased apoptosis in vitro." (PMID 28944088, 2017). "VDR action in prostate cancer has been studied in a limited number of models." (PMID 28591703, 2017). "Interestingly, the number of VDR-positive nucleus in prostate adenoepithelium was significantly decreased in patients with prostate cancer." (PMID 28423553, 2017). "As expected, nuclear VDR in the prostate was reduced in patients with prostate cancer." (PMID 28423553, 2017). "Whether a VDR agonist can reduce the growth of a prostate cancer cell line containing a TMPRSS2:ERG rearrangement in vivo has not been resolved." (PMID 28591703, 2017). "We found that prostatic VDR signaling was attenuated in patients with prostate cancer." (PMID 28423553, 2017).
prostate carcinoma (continued). "This suggests that the mechanism for the enhanced window between inducing VDR activity and causing hypercalcemia is not due to selective activation of a sub-set of VDR target genes within the prostate cancer cell." (PMID 28591703, 2017). "The question of whether VDR agonist would be beneficial or harmful in TMPRSS2:ERG positive prostate cancer has been an important question since we observed that VDR induces its expression." (PMID 28591703, 2017). "Prostatic VDR was then analyzed in patients with prostate cancer and controls." (PMID 28423553, 2017). "There are at least two major challenges in using VDR activation as a therapy in prostate cancer." (PMID 28591703, 2017). "Examining the VDR SNPs, adding rs1544410 and rs731236 to the model did not change the magnitude of the association between aggressive prostate cancer and deficient levels of 25(OH)D (OR: 2.98, 95% CI: 0.98–9.05." (PMID 28036013, 2016). "Although calcium intake alone does not have an association with aggressive disease, the VDR SNP rs11568820 increased the magnitude of the association between 25(OH)D and aggressive prostate cancer." (PMID 28036013, 2016). "Subgroup analyses based on ethnicity, source of controls, and HWE in controls, revealed the absence of prostate cancer risk with VDR ApaI polymorphism." (PMID 27553621, 2016). "Our findings suggest that VDR Cdx2 and ApaI polymorphisms are not linked to prostate cancer susceptibility in the overall population." (PMID 27553621, 2016). "The role of testosterone and vitamin D in prostate cancer is mediated via vitamin D receptor (VDR)." (PMID 27553621, 2016). "We propose that VDR inappropriately recruits co-repressors in prostate cancer cells." (PMID 23098689, 2013). "The astemizole-induced VDR upregulation may be physiologically relevant in models of prostate cancer where a slight increase in VDR synthesis significantly sensitized the cells to calcitriol antineoplastic effects without overt side effects." (PMID 22984610, 2012). "In a study to examine the association between vitamin D receptor (VDR) polymorphisms and prostate cancer stage, the authors concluded that low levels of vitamin D may increase the risk of prostate cancer progression." (PMID 23304521, 2012). "Vitamin D mainly via VDR's genomic effects may suppress prostate cancer cellular dysfunctions including the inhibition of cell proliferation, cell cycle progression, cell invasiveness, angiogenesis, or induction of cell differentiation and apoptosis." (PMID 21991434, 2011). "A case-control study of 630 incident prostate cancer patients was conducted to comprehensively analyze genetic variation in the VDR gene; twenty-two SNPs were genotyped to capture a high percentage of variation in the VDR gene." (PMID 19753122, 2009). "Studying and understanding of the interaction between VDR and LXR/AR is critical for rational design of future clinical trials with vitamin D compounds for prevention and treatment of associated cancers such as prostate cancer." (PMID 19787078, 2008). "VDR seems to play a role in the regulation of prostate cancer cell proliferation." (PMID 19787078, 2008). "This implies that cautions have to be taken whether which of the VDR or LXR signaling was considered for the therapeutic target in prostate cancer." (PMID 19787078, 2008). "We found similar associations between plasma vitamin D metabolites, VDR polymorphisms, and prostate cancer with (as presented above) and without (unpublished data) adjusting for race." (PMID 17388667, 2007). "Therefore, we exploited clinical cohorts to determine whether there was evidence for suppressed VDR signaling in AA prostate cancer progression." (PMID 37082578, 2023). "Therefore, we integrated genomic, transcriptomic, and proteomic datasets, combined with clinical genomic data to reveal how genomic ancestry may impact VDR signaling in prostate cancer." (PMID 37082578, 2023).